NR4A1 (nuclear receptor subfamily 4 group A member 1)
Diseases named in the same sentence as NR4A1 in open-access papers (continued):
Sharing a sentence is not in itself a finding about the gene and the disease.
Obesity (85 papers, 2008 to 2026). Accumulation of substantial excess body fat. "Our findings identify pAkk as a promising postbiotic for obesity-related bone loss and uncover a novel Nr4a1/Treg axis linking gut microbiota to bone homeostasis." (PMID 42254009, 2026). "Accumulating evidence proves that NR4A1 implicated metabolic processes in regulating various diseases, including obesity, atherosclerosis, liver disorders, and diabetes." (PMID 36052242, 2022). "Other novel methylation markers, cg27589809 (CISH), and cg20560869 (NR4A1), are associated with obesity." (PMID 32709145, 2020). "High-fat diet (60% calories from fat) fed mice with genetic deletion of NR4A1 exhibit increased susceptibility to diet-induced obesity and insulin resistance." (PMID 30013988, 2018). "Genetic deletion of NR4A1 increases susceptibility to diet-induced obesity and insulin resistance, and loss of NR4A1 expression in skeletal muscle impairs insulin signaling, markedly reduces GLUT4 protein expression, and increases triglyceride content." (PMID 27322146, 2016). "NR4A1 is also associated with glucose uptake, glycolysis and glycogenolysis, and its global knock-out is associated with an increased predisposition to obesity, insulin resistance and reduced muscle mass." (PMID 33679435, 2021). "Therefore, low NR4A1 expression impairs lipolysis and causes fat accumulation which results in obesity." (PMID 30013988, 2018). "High-fat diet-induced obesity alters the expression of 184 LV genes, highlighting dysregulation of glucose metabolism via Nr4a1." (PMID 41516136, 2025). "NR4A1 also plays an important role in muscle cells, which are prime sites of glucose metabolism and overall insulin sensitivity and obesity." (PMID 40871737, 2025). "Further unbiased research is needed on the molecular mechanisms by which Nr4a1 handles myocardial glucose metabolism homeostasis and subsequently controls cardiac functions in obesity-related cardiovascular pathophysiology." (PMID 32610475, 2020). "Overall, Nr4a1 knockdown interrupted PA-induced impaired glucose homeostasis, highlighting the critical role of Nr4a1 in modulating glucose metabolism homeostasis that is attributed to obesity-induced cardiac injury." (PMID 32610475, 2020). "Overall, we provide a comprehensive understanding of the myocardium transcript molecular framework influenced by HFD and propose Nr4a1 as a key glucose metabolism target in obesity-induced CVD." (PMID 32610475, 2020). "Future studies should clarify the exact role of NR4A1 receptor in metabolism diseases, including obesity, dyslipidemia, and cardiovascular disease, and obtain more novel and effective small molecular compounds based on the structural of NR4A1." (PMID 30013988, 2018). "Genetic studies revealed a critical role of NR4A1 in the control of inflammatory responses, which is highlighted by its protective function in atherosclerosis and obesity." (PMID 30013988, 2018). "In recent years, more and more studies have proved that NR4A1 is involved in the regulation of animal fat metabolism, for instance, NR4A1 knockout mice, compared with wild-type mice, fed with high-fat diet were more prone to obesity." (PMID 39061513, 2024). "Compared with wild mice, NR4A1 knockout mice were more likely obesity." (PMID 38441676, 2024). "In addition, a promising role of Nr4a1 was illustrated as a target in the prevention of obesity-induced CVD." (PMID 32610475, 2020). "NR4A1 expression is significantly decreased in mouse models of obesity and diabetes." (PMID 30013988, 2018). "Moreover, there is also a report showing that female, but not male, NR4A1-deficient mice exhibit increased susceptibility to obesity when maintained on a high-fat diet." (PMID 40871737, 2025). "Furthermore, we propose that Nr4a1 may be a promising therapeutic target for preventing obesity-induced CVD." (PMID 32610475, 2020).
Obesity (continued). "Based on the gene array, we found that skin γδ T cells differentially express NR4A1 and NR4A3, two orphan nuclear receptors which have been shown to sensitize muscle to insulin and have been reported to be underexpressed in obesity and type 2 diabetes." (PMID 20625397, 2010). "Moreover, upregulation of three NRs such as NR4A1, NR4A2, and NR4A3 can be used for the potential biomarkers for obesity while downregulation of NR1D1 can be used as a potential biomarker for obesity with rheumatoid arthritis as a complication." (PMID 29065888, 2017).
invasive ductal carcinoma (67 papers, 2009 to 2026). "The lobular carcinomas in the present series all fell into the grade 2 category and also showed a trend for increase of expression (chi-squared test P = 0.12) of NR4A1 compared with grade 3 primary infiltrating ductal carcinomas." (PMID 20642837, 2010). "Only 14 out of 48 grade 3 infiltrating ductal carcinomas were positive for NR4A1, compared with 23 out of 31 grade 1/2 infiltrating ductal carcinomas (chi-squared test P = 0.0002)." (PMID 20642837, 2010).
lymph node metastasis (61 papers, 2011 to 2026). "Secondly, only 35% of the patients with high-NR4A1 tumors had lymph node metastasis, but more than 48% of the patients with low-NR4A1 tumors developed lymph node metastasis, suggesting that decreased NR4A1 is associated with lymph node metastasis in TNBC patients." (PMID 28903348, 2017).
metastatic disease (54 papers, 2002 to 2026). "Immunohistochemical analysis showed that NR4A1 protein is indeed expressed in tumours but only weakly in normal cells, and interestingly that its expression is downregulated in higher grade and metastatic tumours." (PMID 20642837, 2010). "Breast tissue microarray analysis showed NR4A1 expression in primary tumours, which was reduced in higher grade and metastatic tumours." (PMID 20642837, 2010).
atherosclerosis (49 papers, 2009 to 2026). A disease characterized by the build-up of fatty material and calcium deposition in the arterial wall resulting in partial or complete occlusion of the arterial lumen. "In macrophages, Nr4a1 deficiency increased TNFα production, along with other proinflammatory cytokines, exacerbating inflammation driven atherosclerosis." (PMID 40114913, 2025). "For instance, the loss of Nr4a1 (Nur77) activates macrophages to have an inflammatory phenotype and increases the risk of atherosclerosis." (PMID 39408930, 2024). "In peripheral tissues, NR4A1 acts as an anti-inflammatory molecule in macrophages, and Nr4a1-deficiency enhances the polarization of macrophages into a proinflammatory phenotype and exacerbates atherosclerosis." (PMID 37486903, 2023). "In this study, we first identified DE circRNAs and circRNA-miRNA-mRNA networks associated with angiogenesis in atherosclerosis, after which we verified a novel circSCRG1 and provided evidence, for the first time, that the circSCRG1/miR-1268b/NR4A1 axis regulates ox-LDL-induced angiogenesis in vitro." (PMID 36770940, 2023). "Moreover, Nr4a1 deletion in B cells exacerbates atherosclerosis in association, with an enhanced T follicular helper response." (PMID 36426356, 2022). "Interestingly, specific MZB-cell deletion of Nr4a1 increased atherosclerosis in association with an increased T follicular helper–germinal center response but without any impact on serum cholesterol or triglyceride levels." (PMID 32907369, 2020). "Using a Venn diagram to identify the shared genes, we identified six candidate downstream molecules potentially regulated by AP‐1 and involved in vascular endothelial dysfunction and atherosclerosis induced by OSS: NR4A1, ZNF467, LGAL59, OAS1, OAS2, and TGM2." (PMID 40492401, 2025). "Understanding the GRK2/AP‐1/NR4A1 signaling axis in disturbed flow‐induced vascular endothelial dysfunction and atherosclerosis will aid in the development of novel drugs, offering more targeted and effective treatment options for vascular diseases." (PMID 40492401, 2025). "The loss of NR4A1 in macrophages and monocytes results in enhanced pro-inflammatory M1 macrophages and NR4A1-KO mice maintained on a Western diet developed increased atherosclerosis." (PMID 40871737, 2025). "In atherosclerosis, Nr4a1 is protective as it impairs atherosclerotic plaque formation by opposing smooth muscle and endothelial cell proliferation as well as formation of macrophage-derived foam cells." (PMID 39644367, 2024). "The results of this study confirm circSCRG1 as a new angiogenesis target for plaque instability and circSCRG1/miR-1268b/NR4A1 as a novel angiogenesis signalling pathway in atherosclerosis." (PMID 36770940, 2023). "The overexpression of nuclear receptor subfamily 4 group A member 1 (NR4A1) increased the severity of atherosclerosis through the mitophagy exacerbation that diminished the number of mitochondria and increased endothelial apoptosis." (PMID 37175915, 2023). "Previous studies have primarily focused on the bidirectional roles of NR4A1 in the inflammatory response of atherosclerosis or NR4A1-mediated pro-angiogenic effects in tumour growth and skin wound healing." (PMID 36770940, 2023). "The orphan nuclear receptor Nur77 is a protein encoded by NR4A1 and plays an important regulatory role in cell proliferation, apoptosis, differentiation, inflammation, atherosclerosis, metabolism, DNA repair, and tumorigenesis." (PMID 32982739, 2020). "Specific Nr4a1 deletion in B cells markedly accelerated the development of atherosclerosis in the aortic sinus and the aortic arch." (PMID 32907369, 2020). "While protective in atherosclerosis and myocardial ischemia, Nr4a1 has been shown to cause cardiac fibrosis in non-ischemic adverse remodeling of the heart." (PMID 39644367, 2024).
atherosclerosis (continued). "However, depletion of NR4A1 in B cells markedly promoted cholesterol and triglyceride levels and contributed to atherosclerosis in mice, indicating that the role of NR4A1 is “bidirectional”." (PMID 36977670, 2023). "Therefore, we addressed the role of NR4A1 specifically in MZB cells during the development of atherosclerosis." (PMID 32907369, 2020). "Given that B cells substantially contribute to the development of atherosclerosis, we examined whether NR4A1 regulates B-cell function during atherogenesis." (PMID 32907369, 2020). "Mice deficient in Nur77 (also known as NR4A1), a transcription factor that is shown to be required for Ly6Clo monocyte differentiation and survival, exhibit accelerated atherosclerosis in some studies but not in others." (PMID 31249530, 2019). "NR4A1 has been reported to be involved in the inflammatory disease, atherosclerosis." (PMID 25289075, 2014). "In the present study, NR4A1 was found to be the main target gene of circSCRG1 and the therapeutic target of TMP-PF in the regulation of angiogenesis in atherosclerosis." (PMID 36770940, 2023). "Our data show that NR4A1 expression in MZB cells regulates PDL1 expression, limiting the Tfh-GC response and protecting from atherosclerosis." (PMID 32907369, 2020). "To study the role of Nr4a1 in MZB cells and its impact on atherosclerosis, we generated an atherosclerotic mouse model in which Nr4a1−/− was specifically deleted in MZB cells." (PMID 32907369, 2020). "We have previously reported that the transcription factor NR4A1 regulates nonclassical monocyte development and is necessary for inhibiting NFkB activation in monocytes and macrophages in atherosclerosis." (PMID 38474140, 2024). "Nuclear receptor NR4A1 (Nur77) was reported to be indispensable for monocyte differentiation into M2 macrophage, and the deletion of NR4A1 could increase atherosclerosis." (PMID 34583680, 2021).
endometrial cancer (45 papers, 2001 to 2026). Primary or metastatic malignant neoplasm involving the endometrium (mucous membrane that lines the endometrial cavity). "In endometrial cancer cells where NR4A1 is silenced, the major source of ROS is associated with the downregulation of TXNDC5 and IDH1." (PMID 39000233, 2024). "In the present study, loss of NR4A1 expression co-occurs with existing endometrial cancer subtypes, as we observed a positive relationship between NR4A1 and ESR1 expression." (PMID 32894083, 2020). "Therefore, the inhibition of mTOR signaling in endometrial cancer by NR4A1 antagonists is largely attributed to the downregulation of TXNDC5 and the consequent induction of ROS." (PMID 38666927, 2024). "NR4A1 has no known associations with endometrial cancer, though previous studies have identified roles for NR4A1 in other cancers." (PMID 32894083, 2020). "Similarly, Nr4a1 overexpression in Ishikawa cells, an endometrial cancer line, decreased proliferation, while Nr4a1 knock down increased proliferation." (PMID 31683815, 2019). "Studies on the NR4A1 antagonist activities of CDIMs demonstrate that treatment of colon, lung, breast, pancreatic, kidney, RMS, and endometrial cancer cells with CDIM/NR4A1 antagonist inhibited the pro-oncogenic NR4A1-regulated functional responses (rev in 27)." (PMID 34906197, 2021).
melanoma (45 papers, 2010 to 2026). A malignant, usually aggressive tumor composed of atypical, neoplastic melanocytes. "The NR4A1-dependent metabolic adaptation protects melanoma cells undergoing loss of attachment (LOA) to the ECM and supports the survival of circulating tumor cells in the circulation." (PMID 33634114, 2021). "Phosphoserine phosphatase reduces 2-hydroxyglutarate levels and inhibits histone demethylases in melanoma cells, upregulates NR4A1 expression and promotes tumor growth and metastasis." (PMID 40666103, 2025). "Instead, we found a significant increase in NK cells in metastatic melanoma colonies after NOD2-dependent LY6Clo I-NCMs were adoptively transferred into Nod2–/– mice or after MDP treatment of Nr4a1–/– mice." (PMID 39545417, 2024). "Collectively, these findings highlight the potential involvement of NR4A1 in the immune suppression of human melanomas." (PMID 38334978, 2024). "We found more extravascular B16F10 melanoma cells in Nod2–/– or Nr4a1–/– than in WT mice, indicating increased engraftment." (PMID 39545417, 2024). "Overall, NR-V04–mediated NR4A1 degradation holds promise for enhancing anticancer immune responses and offers a new avenue for treating various types of cancers such as melanoma." (PMID 38334978, 2024). "Nod2–/– and Nr4a1–/–Nod2–/– double-mutant mice showed a pronounced increase in tumor seeding and progression of melanoma metastasis in the lungs compared with Nr4a1–/– and WT mice." (PMID 39545417, 2024). "We have identified that NR4A1 is highly elevated in human TI-Tregs and others have found NR4A1 expression in TI-Tregs from melanoma." (PMID 39872303, 2023). "Mitochondrial NR4A1 is also known to bind to thyroid hormone receptor β and promotes cell survival of melanoma cells under metabolic stress." (PMID 39872303, 2023). "Melanoma cells have a well-defined stressed cell state, which is marked by the upregulation of immediate early transcription factors (JUN, FOS, ATF3, NR4A1, DUSP) linked to melanoma oncogenic programs, inflammation, and stress response." (PMID 36765834, 2023). "Knockout of NR4A1 in the host mice results in decreased angiogenesis in B16 mouse melanoma tumor models." (PMID 39872303, 2023). "Other studies have shown that NR4A1 is induced by oncogenic serine/threonine-protein kinase B-raf (BRAF) in melanoma cells and is involved in promoting the proliferation, survival, and invasiveness of melanoma cells." (PMID 39872303, 2023). "In contrast, in a study of melanoma, NR4A1 contributes to the metabolic adaptation of melanoma cells by regulating fatty acid uptake and oxidation." (PMID 33634114, 2021). "Among NR4A subfamily members, the function of NR4A1 is the most known, and NR4A1 acts as an oncogene or a tumor suppressor in diverse cancer models, such as colon cancer, liver cancer, lung cancer, melanoma, and acute myeloid leukemia." (PMID 34209871, 2021). "In melanoma, Nr4a1 translocates to the mitochondria and stabilize TPβ of the mitochondrial trifunctional protein through direct binding." (PMID 31683815, 2019). "Nr4a1 levels were decreased in primary melanoma tissue, possibly leading to protection from apoptotic treatments." (PMID 31683815, 2019). "To achieve this we used a cutaneous melanoma cell line previously found to have low levels of NR4A1 and NR4A2 expression by real time PCR and EMSA." (PMID 24223135, 2013). "While NR4A1 is expressed in melanoma tissues, its expression appears to decline in metastatic melanomas." (PMID 20642837, 2010). "Furthermore, in melanoma, colon, and lung cancers, inhibiting NR4A1 in cytotoxic CD8+ T cells results in a decrease in tumor infiltration and progression." (PMID 40508074, 2025). "NR4A1 regulated the linkage FAO-NADPH-ROS during metabolic stress to target melanoma." (PMID 36052242, 2022).